CCL20 (C-C motif chemokine ligand 20)
Diseases named in the same sentence as CCL20 in open-access papers (continued):
Sharing a sentence is not in itself a finding about the gene and the disease.
breast cancer (continued). "For instance, breast cancer cells were shown to express CCL20 and this expression negatively correlated with survival in patients." (PMID 31572390, 2019). "Multivariate Cox regression analysis indicated that both FOXP3 and CCL20 are independent prognostic factors for OS of breast cancer patients." (PMID 31852159, 2019). "We further evaluated the effects of FOXP3 and CCL20 expression on survival outcomes in breast cancer patients under different lymph node metastasis status." (PMID 31852159, 2019). "The activation of p38 MAPK and PKCζ via phosphorylation was also increased by CCL20 overexpression in breast cancer cells." (PMID 30052635, 2018). "CCL20 can be induced by taxane and promoted the development of breast cancer, which, considering the relationship between CCL20 and pCR, prompted us to further observe impact of CCL20 on chemotherapy resistance." (PMID 30052635, 2018). "Increasing levels of CCL20 result in expanding breast cancer stem-like cell population and chemotherapeutic resistance in breast cancer cells." (PMID 30052635, 2018). "Through studies analyzing breast cancer patients’ serum, tumor tissue sample, survival prognosis, and pathologic response to taxane, we identified a chemokine, C-C motif chemokine ligand 20 (CCL20), that might predict the risk of taxane resistance in TNBC patients." (PMID 30052635, 2018). "These discoveries shed light on direct targeting CCL20 or small molecule inhibition of CCL20-induced signaling being able to potentiate chemotherapeutic efficacy in breast cancer." (PMID 30052635, 2018). "Here in our study, after overexpression of CCL20, an increase in p65 NF-κB activation by phosphorylation was observed in breast cancer cells." (PMID 30052635, 2018). "To examine how CCL20 contributes to bone metastasis of breast cancer cells, we evaluated the effects of CCL20 treatment on the proliferation, migration, and invasion of MDA-MB-231 cells." (PMID 28851919, 2017). "Here, HuR knockdown inhibited bone metastasis and osteolysis of metastatic breast cancer cells in mice and HuR expression promoted the metastatic ability of cancer cells via CCL20 and GM-CSF." (PMID 28851919, 2017). "We further identified that the metastatic ability of HuR-expressing breast cancer cells was related to their secretion of CCL20 and GM-CSF." (PMID 28851919, 2017). "Metastasis-free survival and overall survival were decreased in the breast cancer patients with high CCL20 expression." (PMID 28851919, 2017). "Kaplan-Meier survival analysis of GSE3494, GSE7390 and GSE26971 showed that metastasis-free survival and overall survival were decreased in the breast cancer patients with high CCL20 expression." (PMID 28851919, 2017). "Paracrine CCL20 has been shown to induce epithelial-mesenchymal transition in breast cancer and CCL5 has been shown to promote vascular endothelial growth factor VEGF-induced angiogenesis." (PMID 29215599, 2017). "Intraperitoneal administration of anti-CCL20 antibodies inhibited osteolytic breast cancer bone metastasis in mice." (PMID 28851919, 2017). "Collectively, CCL20, which is regulated by HuR and secreted into the bone microenvironment, enhances the metastatic ability and bone metastasis of breast cancer cells by stimulating cancer cells and osteoblastic cells in both autocrine and paracrine manners." (PMID 28851919, 2017). "Here, we demonstrate that HuR-regulated CCL20 are attractive targets for breast cancer bone metastasis." (PMID 28851919, 2017). "Taken together, our results suggest that HuR in breast cancer cells regulates the production of CCL20 and GM-CSF and that the secretion of these chemokines promotes cancer cell migration and invasion." (PMID 28851919, 2017). "In breast cancer, CCL20 was found to be expressed by cancer cells and correlate with infiltration by immature DC." (PMID 21624121, 2011). "Furthermore, CCL20-induced PMN-MDSCs increased breast cancer stemness and drug resistance to docetaxel via CXCL2/CXCR2." (PMID 39985603, 2025).
breast cancer (continued). "CCL20 has become of great interest in tumor research as it promotes tumor progression in different solid tumor entities, including cervical carcinoma, pancreatic ductal adenocarcinoma, cutaneous squamous cell carcinoma and breast cancer." (PMID 38730689, 2024). "Previous studies found that CCL20 can be a novel predictive marker for taxanes response, and blockade of CCL20 or its downstream pathway might reverse the taxanes resistance in breast cancer patients." (PMID 36045408, 2022). "As we gain such new insights, disrupting CCL20 promoting networks could provide novel therapeutic strategies for breast cancer treatment." (PMID 34569432, 2021). "Emerging studies have demonstrated notable roles of CCL20 in breast cancer progression." (PMID 34569432, 2021). "Their results showed that Jinrong granule could inhibit the ability of CXCL-1 to promote the migration and proliferation of breast cancer cells and it could also reverse the promoting effect of CXCL-1 on breast cancer through the CXCL-1- CLCR2/CCL20 pathway." (PMID 34737734, 2021). "This reveals new insight into the role of CCL20 in breast cancer pathogenesis." (PMID 34519637, 2021). "Importantly, it has also been shown the NF-κB activation by CCL20 can in turn increase further CCL20 expression to form a positive feedback loop between NF-κB and CCL20 pathways in these breast cancer cells." (PMID 33483477, 2021). "Our findings suggest that targeting TANs via CCL20 immunosuppressive pathway may be a novel therapeutic strategy for breast cancer treatment." (PMID 34519637, 2021). "First, CCL20 secreted by breast cancer cells activates and induces PD-L1 expression on neutrophils." (PMID 34519637, 2021). "Further in agreement with this notion, accumulation of CCL20 has been demonstrated to be able to promote the self-renewal and maintenance of breast cancer stem cells (BCSCs) through p38 mitogen-activated protein kinase (MAPK)-mediated activation of p65 nuclear NF-κB pathway." (PMID 33483477, 2021). "These new insights may be useful to design new potent and selective CCL20 inhibitors against breast cancer in the future." (PMID 34569432, 2021). "Thus, CCL20 mRNA and protein levels are higher in human cell lines representing breast cancer, melanoma and HNSCC compared with the corresponding primary (untransformed) cells." (PMID 32601464, 2020). "High CCL20 levels contribute to the formation of bone metastases in breast cancer." (PMID 32321535, 2020). "In addition, tumour progression and poor survival of breast cancer patients correlate with CCL20 expression." (PMID 32601464, 2020). "In addition, in breast cancer patients, we observed a significant correlation between high CCL20 expression and adverse survival rates." (PMID 32601464, 2020). "One study has shown that intraperitoneal administration of anti-CCL20 antibody has inhibited osteolytic breast cancer bone metastasis in a mouse model, and CCL20 has significantly enhanced cell invasion and secretion of matrix metalloproteinase (MMP) 2 and 9 in TNBC cell lines." (PMID 32707869, 2020). "This shows that in breast cancer, CCL20 may be important in in situ recruitment or retention of FOXP3+ Tregs." (PMID 31852159, 2019). "In this study, the immunohistochemical results showed that in breast cancer patients, high CCL20 expression and increased FOXP3+ TILs infiltrates were both associated with high histological grade, axillary lymph node metastases, positive HER2, and high Ki67 index." (PMID 31852159, 2019). "In line with this, treatment of a breast cancer bone metastasis mouse model with a neutralizing anti-CCL20 antibody could inhibit metastasis and osteolysis." (PMID 31572390, 2019). "In addition, we discovered CCL20 also exhibited strengthening in resistance to taxane, demonstrating its pivotal role in the regulation of breast cancer malignancy." (PMID 30052635, 2018). "In conclusion, high expression of CCL20 predicts worse prognosis in breast cancer patients." (PMID 30052635, 2018).
breast cancer (continued). "Therefore, we observed the pharmacological distribution and abundance of docetaxel in breast cancer cells after overexpression of CCL20 by high-performance liquid chromatography–mass spectrometry (HPLC-MS)." (PMID 30052635, 2018). "In addition, NF-κB activation increased CCL20 expression, forming a positive feedback loop between NF-κB and CCL20 pathways, which provides sustained impetus for chemoresistance in breast cancer cells." (PMID 30052635, 2018). "Little work has revealed the regulation of CCL20 on breast cancer." (PMID 30052635, 2018). "More importantly, little work has been done on the role of CCL20 in regulating the tumor progression and chemoresistance in breast cancer, especially TNBC, and the regulation mechanisms still remain unknown." (PMID 30052635, 2018). "Our results suggest that CCL20 can be a novel predictive marker for taxane response, and the blockade of CCL20 or its downstream pathway might reverse the taxane resistance in breast cancer patients." (PMID 30052635, 2018). "However, consistent with results from breast cancer patient serum, cytokine levels in the mouse sera were significantly changed when receiving the taxane treatment, among which CCL20 was obviously observed." (PMID 30052635, 2018). "These suggest that CCL20 may confer taxane resistance in various molecule types of breast cancer and even across multiple cancers, in which further exploration and study are needed." (PMID 30052635, 2018). "Collectively, HuR-regulated CCL20 may be an attractive therapeutic target for breast cancer bone metastasis." (PMID 28851919, 2017). "Moreover, CCL20 elevated the receptor activator of nuclear factors kappa-B ligand/osteoprotegerin ratio in breast cancer and osteoblastic cells and mediated the crosstalk between these cells." (PMID 28851919, 2017). "We further confirmed the role of CCL20 in breast cancer bone metastasis." (PMID 28851919, 2017). "In addition, the production of CCL20 and GM-CSF in various breast cancer cell lines, including the luminal B and basal-like/triple-negative breast cancer subtypes, was also regulated by HuR." (PMID 28851919, 2017). "To clarify whether CCL20 and GM-CSF are critical factors that mediate the function of HuR in breast cancer bone metastasis, we added antibodies specific to these chemokines to culture media of MDA-MB-231 cells." (PMID 28851919, 2017). "To assess whether CCL20 could serve as a novel therapeutic target for bone metastasis of breast cancer cells, we inoculated luciferase-transfected MDA-MB-231 cells into the left cardiac ventricles of nude mice." (PMID 28851919, 2017). "According to our findings, Syndecan-1 silencing in triple-negative MDA-MB-231 breast cancer cells inhibited proinflammatory signaling via downregulation of relevant receptors and ligands (IL-6/IL6-R/CCL20), which was linked to reduced constitutive activation of NFkB and STAT3." (PMID 24392029, 2013). "Recent studies on breast cancers have shown that two of these chemokines, CCL20 and CCL22, may recruit Treg that express the corresponding chemokine receptors CCR6 and CCR4." (PMID 21521526, 2011). "However, it is unclear whether CCL20 affects breast cancer progression by remodeling the tumor microenvironment (TME)." (PMID 36859354, 2023). "Therefore, we hypothesize that CCL20 secreted by breast cancer cells can promote immunosuppressive functions of neutrophils." (PMID 34519637, 2021). "Collectively, targeting CCL20 could promote chemotherapeutic efficacy in breast cancer." (PMID 34569432, 2021). "However, the mechanism of reprogramming dendritic cells by CCL20 remains unknown and warrants further studies in breast cancer." (PMID 34569432, 2021). "Hence, we wanted to determine whether tumor-derived CCL20 can induce PD-L1 expression on neutrophils in breast cancer." (PMID 34519637, 2021). "CCL20 intervention may improve taxane therapy for breast cancer, including TNBCs." (PMID 30052635, 2018).
breast cancer (continued). "Although the cell type that secretes CCL20 is unknown in the PyMT model, a recent study demonstrates that MDA-MB-231 human breast cancer cells express high level of CCL20 and that inhibition of CCL20 expression in cancer cells reduces TAM accumulation in xenografts." (PMID 30483271, 2018). "Interestingly, we found that CCL20 was the most universally and significantly up-regulated in common, suggesting CCL20 might play a vital role in regulating the taxane resistance of breast cancer cells." (PMID 30052635, 2018). "Thus, CCL20 may have high potential as a therapeutic target in breast cancer patients with bone metastasis." (PMID 28851919, 2017). "CCL20, a chemokine involved in the JAK-STAT signaling pathway, has been shown to influence cell migration and invasion in breast cancer (Muscella, Vetrugno & Marsigliante, 2017)." (PMID 40444282, 2025). "Our previous studies have showed that C-C motif chemokine ligand 20 (CCL20) advanced tumor progression and enhanced the chemoresistance of cancer cells by positively regulating breast cancer stem cell (BCSC) self-renewal." (PMID 36859354, 2023). "Collectively, these results indicated that CCL20-modulated PMN-MDSCs enhanced the stemness and self-renewal ability of breast cancer cells." (PMID 36859354, 2023). "CCL20-modulated PMN-MDSCs secreted amounts of CXCL2 and activated NOTCH1/HEY1 signaling pathway in breast cancer cells by binding to CXCR2, leading to the increase of ALDH+ BCSCs." (PMID 36859354, 2023). "Taken together, we confirmed that CXCL2-CXCR2 axis, which was activated by CCL20-modulated PMN-MDSCs, enhanced the stemness of breast cancer cells by NOTCH1/HEY1 signaling pathway." (PMID 36859354, 2023). "To explore the mechanism that CCL20-modulated PMN-MDSCs promoted stemness of breast cancer cells, we sorted tumor cells and PMN-MDSCs from pSIN-/CCL20-overexpressing 4T1 cell allograft tumors and examined the transcriptome profiling via RNA-Seq." (PMID 36859354, 2023). "Hence, targeting TANs via CCL20 may be a novel therapeutic strategy for breast cancer treatment." (PMID 34519637, 2021). "In a recent study exploring downstream regulators of notch signaling in the metastasis processes of breast cancer, silencing notch in MDA-MB-231 cell lines significantly inhibited the mRNA expression of CCL20." (PMID 34569432, 2021). "CCL20, the sole receptor of CCR6, plays a direct role in the progression of several solid tumors, including breast cancer." (PMID 34519637, 2021). "To correlate the observed CCL20 mRNA levels with protein expression, we investigated CCL20 protein levels in supernatants from HNSCC, melanoma and breast cancer cell lines using ELISA." (PMID 32601464, 2020). "In 334 cases of breast cancer, colon carcinoma and HNSCC, a higher pT category of the observed tumours correlated significantly to higher expression of CCL20." (PMID 32601464, 2020). "CCL7, CCL17, CCL20 and CCL25 are significantly more elevated in AA breast cancer patients compared to CA patients." (PMID 32824813, 2020). "In cancer tissues, including breast cancer, colon carcinoma, head and neck SCC and melanoma, our results indicate that CCL20 is a chemokine preferably expressed in advanced tumour stages." (PMID 32601464, 2020). "Although there is no direct evidence supporting CXCL10 and CCL20-mediated TAM infiltration in prostate cancer, CXCL10 and CCL20 promote TAM recruitment in colorectal and breast cancer, respectively." (PMID 32971847, 2020). "In comparison with mammary epithelial cells, CCL20 expression was higher in MDA-MB-468 and MDA-MB-361, was comparable in MCF-7 and T-47D and was lower in DU-4475 and Hs578T breast cancer cells." (PMID 32601464, 2020). "Univariate analysis of pathological features, CCL20 expression, and FOXP3+ TILs infiltration with OS and DFS in breast cancer patients (n = 156)." (PMID 31852159, 2019). "In addition, CCL20/CCR6 may also be potential therapeutic targets for breast cancer." (PMID 31852159, 2019).
breast cancer (continued). "CCL20 and FOXP3+ TILs mRNA expression in tumor tissue demonstrated a high correlation (rs = 0.359, P < .001) in this cohort of breast cancer patients." (PMID 31852159, 2019). "CCL20, also called LARC or MIP3A, is one of small cytokines and plays key roles in the development of various cancers, such as prostate cancer, breast cancer and so on." (PMID 30760665, 2019). "Chemokines with well-known functions in mammary cancer include CCL2, CCL5, CCL19, CCL20, CCL21 and CCL22." (PMID 30572845, 2018). "Taken together, we identified a taxane-induced cytokine CCL20, and its expression level in serum and tumor tissue showed a positive correlation with the poor pathologic response to NAC in breast cancer patients." (PMID 30052635, 2018). "Taken together, CCL20 drives the self-renewal and expansion of ALDH+ population to promote the properties of BCSCs, leading to the increased taxane resistance of breast cancer cells." (PMID 30052635, 2018). "Together, these studies demonstrated that taxane-induced CCL20 activated NF-κB through PKCζ or p38 and then promoted the expression of ABCB1, leading to the chemoresistance of breast cancer cells." (PMID 30052635, 2018). "For example, it is reported that CCL20, a ligand for CCR6, is abundant in PyMT mammary tumors and genetic deletion of Ccr6 gene in PyMT mice significantly reduces the number of TAMs in mammary tumors." (PMID 30483271, 2018). "Thus, CCL20 may be a better target for breast cancer bone metastasis than GM-CSF." (PMID 28851919, 2017). "We found that CCL20 enhanced the RANKL/OPG ratio by stimulating RANKL expression and secretion and reducing OPG expression and secretion in MDA-MB-231 human breast cancer cells in a dose-dependent manner." (PMID 28851919, 2017). "Further, the osteoblastic cells produced CCL20, and the antibody-mediated neutralization of osteoblastic cell-derived CCL20 significantly inhibited the invasiveness of MDA-MB-231 breast cancer cells." (PMID 28851919, 2017). "In summary, we demonstrate that metastatic breast cancer patients have an increased frequency of circulating KIT+CD11b+ cells, M2-polarized CD11b+ cells and elevated levels of the M2 cytokine IL-10 and CCL20." (PMID 26840567, 2016). "CCL20 is involved in promoting tumor growth, migration and EMT transition in breast cancer in vitro models and it also plays a role in recruiting immature dendritic cells and in tumor-promoting Tregs in other cancer types." (PMID 26840567, 2016). "Chemokines CCL19, CCL20 and CCL21 and their receptors CCR6 and CCR7, were assessed as potential biomarkers of metastatic dissemination in primary breast cancer." (PMID 21624121, 2011). "Further studies, using different techniques such as quantitative RT-PCR or protein extraction on frozen samples, will be needed to accurately assess the expression of CCL20 and CCL21 in primary breast cancer." (PMID 21624121, 2011). "Previous studies have shown that CCL20 mediates the JAK-STAT signaling pathway, influencing migration and invasion in breast cancer cells (Muscella, Vetrugno & Marsigliante, 2017), and that berberine inhibits apoptosis in gastric cancer via the JAK-STAT pathway." (PMID 40444282, 2025). "CCL20-regulated PMN-MDSCs secrete large amounts of CXCL1 by binding to CXCR2 and activating the NOTCH1/HEY2 signaling pathway in BC cells, leading to an increase in breast cancer stem cells (BCSCs)." (PMID 38609997, 2024). "Together, our results suggest that tumour-derived CCL20 promotes tumour progression and growth, and has a corresponding negative effect on the survival of breast cancer patients." (PMID 32601464, 2020). "In addition, significant correlation between CCL20 expression and FOXP3+ TILs infiltration in breast cancer tissue was identified (rs = 0.359, P < .001)." (PMID 31852159, 2019). "The results suggest that CCL20 and FOXP3+ TILs may have synergistic effects, and their upregulated expressions may lead to immune evasion in breast cancer." (PMID 31852159, 2019).